C2orf68 (chromosome 2 open reading frame 68)
Synonyms: HCRCN81
Tractability: No criterion of Open Targets' tractability assessment is met for any kind of drug.
Gene: Protein-coding gene on chromosome 2 (85,605,254 to 85,612,066, reverse strand). Ensembl gene ENSG00000168887.
Subcellular location (Human Protein Atlas): Mitochondria; Nuclear membrane; Nucleoplasm; Nucleoli
Gene Ontology:
Molecular function: protein binding
Genetic constraint (gnomAD): Loss-of-function variants: 15 observed, 19.61 expected, observed/expected ratio (o/e) 0.76, 90% interval 0.51 to 1.18. The upper end of that interval is the gene's LOEUF score, 1.18, which puts it in group 5 of 6, group 1 being the genes least tolerant of losing a copy. Missense variants: 242 observed, 220.73 expected, observed/expected ratio (o/e) 1.1, 90% interval 0.99 to 1.22. Synonymous variants: 98 observed, 88.23 expected, observed/expected ratio (o/e) 1.11, 90% interval 0.94 to 1.31.
Homologues: Orthologues: chimpanzee C2AH2orf68 (98% identical), macaque C13H2orf68 (98% identical), dog C2orf68 (89% identical), rat C4h2orf68 (87% identical), pig C2orf68 (86% identical), mouse 0610030E20Rik (83% identical), guinea pig C2orf68 (74% identical), zebrafish C5H2orf68 (49% identical), tropical clawed frog c3h2orf68 (43% identical).
Diseases named in the same sentence as C2orf68 in open-access papers:
C2orf68 is named in the same sentence as 1 disease in open-access papers, as found by Europe PMC text mining. Sharing a sentence is not in itself a finding about the gene and the disease.
C2orf68 shares sentences with these, for which no sentence is quoted: schizophrenia (1 paper).